APOC4-APOC2 (APOC4-APOC2 readthrough (NMD candidate))
Gene: Protein-coding gene on chromosome 19 (44,942,238 to 44,949,565, forward strand). Ensembl gene ENSG00000224916.
Genetic constraint (gnomAD): Loss-of-function variants: 16 observed, 21.99 expected, observed/expected ratio (o/e) 0.73, 90% interval 0.49 to 1.11. The upper end of that interval is the gene's LOEUF score, 1.11, which puts it in group 4 of 6, group 1 being the genes least tolerant of losing a copy. Missense variants: 204 observed, 216.85 expected, observed/expected ratio (o/e) 0.94, 90% interval 0.84 to 1.06. Synonymous variants: 91 observed, 90.88 expected, observed/expected ratio (o/e) 1, 90% interval 0.84 to 1.19.